TRIM75 (tripartite motif containing 75)
Description:
May play a role in female meiosis.
Synonyms: TRIM75P
Tractability: No criterion of Open Targets' tractability assessment is met for any kind of drug.
Gene: Protein-coding gene on chromosome 4 (165,053,866 to 165,060,554, forward strand). Ensembl gene ENSG00000250374.
Subcellular location: Cytoplasm, cytoskeleton, spindle
Gene Ontology:
Molecular function: ubiquitin protein ligase activity; zinc ion binding
Biological process: female meiosis I; innate immune response; regulation of gene expression
Cellular component: extracellular region; cytoplasm; nucleus; spindle
Homologues: Orthologues: chimpanzee TRIM75 (99% identical), macaque TRIM75 (97% identical). Paralogues in human: TRIM61 (48% identical), TRIM60 (47% identical), TRIM39 (34% identical), TRIM68 (33% identical), TRIM41 (30% identical), TRIM27 (29% identical), TRIM38 (29% identical), TRIM11 (29% identical), TRIM21 (29% identical), TRIM6 (28% identical), TRIM4 (28% identical), TRIM58 (27% identical), and 68 more.